IL33 (interleukin 33)
Diseases named in the same sentence as IL33 in open-access papers (continued):
Sharing a sentence is not in itself a finding about the gene and the disease.
colitis (continued). "IL-33 treatment decreases inflammatory bowel symptoms in trinitrobenzene sulfonic acid-induced colitis." (PMID 36291105, 2022). "Conversely, treatment with IL-33 or transfer of ILC2s improve intestinal mucosal damage through the AREG pathway in the DSS-induced colitis model." (PMID 35707544, 2022). "IL-33 promotes intestinal IgA production by B cells which is required for intestinal homeostasis and prevention of colitis." (PMID 36263033, 2022). "It is likely that IL25 promotes colitis in an IL33 dependent manner on C57BL/6J, but promotes IL13 in BALB/c, which leads to the differences between the disparate strains." (PMID 35359953, 2022). "IL-33 promotes intestinal intraepithelial PD-L1+ Breg cells which sustains intestinal homeostasis and prevents colitis." (PMID 36263033, 2022). "Genetic ablation of ST2, a receptor of IL-33, resulted in amelioration of colitis induced by DSS or trinitrobenzene sulfonic acid." (PMID 35707544, 2022). "In acute DSS colitis, it was shown in mice that IL-33 stimulation triggers ILC2s to secrete AREG, a ligand of the EGF receptor." (PMID 36430676, 2022). "In experimental colitis, IL-33 induced ILC2 activation, resulting in GC hyperplasia that contributes to epithelial structural restoration." (PMID 34581755, 2021). "IL-33 exacerbates TNBS-induced colitis by disrupting the intestinal barrier function and promoting Th1 responses." (PMID 34759844, 2021). "The complex function of IL-33 in the intestine and the variety of different target cells seem to pose a challenge for the use of IL-33 as a therapeutic drug during colitis." (PMID 34335571, 2021). "To first evaluate the role of IL-33-mediated Treg expansion on the course of DSS-induced colitis, we used DEREG/c mice to specifically deplete Foxp3+ Tregs by applying diphtheria toxin (DT)." (PMID 34335571, 2021). "Taken together, the absence of the IL-33/ST2 pathway augmented disease severity, suggesting a host-protective role for IL-33 during DSS-induced colitis." (PMID 34335571, 2021). "Studies using colitis mouse models have shown that administration of recombinant IL-33 ameliorates intestinal inflammation." (PMID 33654214, 2021). "Recently, IL-33, as an IL-1 family cytokine and alarmin was ascribed a unique and essential role during colitis development." (PMID 34335571, 2021). "On the one hand, IL-33 is considered to aggravate intestinal pathology, but on the other hand, it has been shown that IL-33 is able to attenuate colitis development, a characteristic of IL-33 that was also observed for other disease patterns." (PMID 34335571, 2021). "In contrast, Zhu showed that IL-33 induced DSS-induced colitis in mice by promoting Th2 response and inhibiting Th1 response in the mesenteric lymph node (MLN)." (PMID 33462754, 2021). "In conclusion, the primary source of IL-33 in the mouse colon, at baseline and during acute colitis induced by epithelial injury, is mucosal fibroblasts." (PMID 33953267, 2021). "Accordingly, in a mouse model of Dextran Sulfate Sodium (DSS) induced colitis, the secretion of IL-33 significantly accelerated in the colon." (PMID 34335571, 2021). "Since previous studies have shown a protective role for IL-33 in DSS-induced colitis, we compared Il33 induction in Il10−/− chronic colitis and DSS-induced acute colitis." (PMID 33953267, 2021). "Even though several studies highlight the IL-33/ST2 pathway as a key factor in colitis, a detailed mode of action remains elusive." (PMID 34335571, 2021). "We sought to determine which IL-33-citrine+ fibroblast population was increasing during DSS-induced colitis." (PMID 33953267, 2021). "ST2−/− mice exhibit reduced disease severity in colitis models and administration of exogenous IL-33 aggravates the disease." (PMID 33435303, 2021). "In summary, our results emphasize that the IL-33/ST2 pathway plays a crucial protective role in colitis by modulating ILC2 and Treg numbers." (PMID 34335571, 2021).
colitis (continued). "In summary, in this study we highlight the potential of exogenous IL-33 application during acute colitis and its essential role for promoting ILC2 activation to restrain intestinal inflammation." (PMID 34335571, 2021). "Since IBD is characterized by uncontrolled activation of intestinal immune cells, we further assessed the impact of IL-33 on ST2+ immune cells during DSS-induced colitis." (PMID 34335571, 2021). "Many studies have explored the role of IL-33 in acute murine models of colitis or recovery from colitis, but there is a paucity of studies in models of chronic colitis." (PMID 33953267, 2021). "To further elucidate the role of IL-33 during intestinal inflammation, we applied the DSS-induced colitis model to ST2 deficient (ST2-/-) mice." (PMID 34335571, 2021). "Since Il33 expression increases in DSS-induced colitis, we examined IL-33-citrine+ cells in DSS-exposed and unchallenged Il33Cit/+mice by flow cytometry." (PMID 33953267, 2021). "Another study also showed that administration of IL-33 ameliorated TNBS colitis through the downregulation and upregulation of Th1 and FOXP3+ Treg responses, respectively." (PMID 34759844, 2021). "Depletion of Foxp3+ Tregs during IL-33 treatment in DSS colitis ameliorated the positive effect on the intestinal pathology." (PMID 34335571, 2021). "We expected to find a protective role for IL-33 in chronic colitis due to its protective role in other models of colitis, including our previous study in oxazolone colitis." (PMID 33953267, 2021). "claim that IL-33 triggers a Th1-to-Th2/Treg switch, which mediates improved colon pathology, we propose that IL-33-induced alleviation of DSS colitis is only partially dependent on Tregs." (PMID 34335571, 2021). "The results presented here support the role of IL-33 as a potential therapeutic target during the acute phase of colitis, given the striking protection promoted by exogenous IL-33 treatment." (PMID 34335571, 2021). "In the present study, we used the murine DSS model to determine the function of IL-33 during acute colitis." (PMID 34335571, 2021). "Overall, our results suggest that ILC2s facilitate IL-33-mediated tissue protection in DSS colitis, while Tregs seem to play an ILC2-supporting role." (PMID 34335571, 2021). "The concentrations of proinflammatory cytokines IL-1β, IL-6, and CCL-2 in the colonic tissues of colitis mice decreased significantly, while anti-inflammatory cytokines IL-33 and IL-10 increased significantly." (PMID 34567209, 2021). "To determine the role of IL-33 in a spontaneous chronic model of colitis, we crossed Il10−/− mice to Il33−/− to generate Il10−/−Il33−/− mice." (PMID 33953267, 2021). "IL-33 is upregulated in ulcerative colitis and has a protective role in chemically-induced acute murine colitis." (PMID 33953267, 2021). "In summary, our findings highlight the relevance of IL-33 during intestinal inflammation and support its potential as a therapeutic drug to restrain colitis." (PMID 34335571, 2021). "Administration of IL-33 inhibited the development of T cell transfer colitis by the expansion of FOXP3+ Tregs." (PMID 34759844, 2021). "Taken together, our study suggests that IL-33 proliferating ILC2 can exert a therapeutic role in mouse colitis." (PMID 32676507, 2020). "In models of CT26 cell engraftment and colitis-associated CRC, tumor growth was reduced after IL-33 treatment." (PMID 32923137, 2020). "In the AOM+DSS colitis-associated CRC model, IL-33 was applied one week after the last cycle of DSS in order not to interfere with the (inflammatory) effect of DSS." (PMID 32923137, 2020). "Collectively, these results demonstrated that IL-33 ameliorates experimental colitis through, at least in part, regulating autophagy in mice." (PMID 30651971, 2019). "We have previously demonstrated that IL-33 ameliorates experimental colitis through promoting Th2/Foxp3+ Treg responses in mice." (PMID 30651971, 2019).
colitis (continued). "A role of increased expression of amphiregulin by IL-33 has been shown to contribute to control experimental colitis, which merits further investigations." (PMID 31057534, 2019). "Two independent studies demonstrated that exogenous IL-33 attenuated TNBS-induced colitis, protective phenotypes which were attributed to the induction of either TH2/TREGS or M2 macrophages, respectively." (PMID 31231388, 2019). "For instance, one particular study showed that administration of recombinant IL-33 exacerbated acute colitis, but ameliorated colitis in a chronic model of disease in a manner dependent on amphiregulin-EGFR signaling." (PMID 31139196, 2019). "In the present study, we investigated the effects and mechanisms of IL-33 on experimental colitis induced by TNBS in mouse." (PMID 30651971, 2019). "This has been shown in a model of TNBS colitis, whereby recombinant IL-33 administration was shown to attenuate disease development through induction of M2-like macrophage polarization." (PMID 31139196, 2019). "In the context of DSS-induced colitis, IL-33 plays a varying role depending on the temporal stage of the disease." (PMID 31139196, 2019). "What are the possible mechanisms by which IL-33 enhancing autophagy alleviate TNBS-induced experimental colitis?" (PMID 30651971, 2019). "IL-33 is a well-known regulator of mucin responses in multiple inflammatory settings, but our colitis model largely found IL-13- and IL-22-dependent signaling." (PMID 30518915, 2018). "On the other hand, administration of IL-33 protected mice in experimental colitis through expansion of Tregs, and induction of AREG expression in gut ILC2." (PMID 30213101, 2018). "The recent study showed that IL-33-induced M2-type macrophage attenuates the development of TNBS-induced colitis." (PMID 30539029, 2018). "So, the level of Breg responses promoted by IL-33 was higher in the chronic phase of colitis than the acute phase." (PMID 30539029, 2018). "To directly assess the role of IL-33 in colitis development, we administered recombinant IL-33 i.p. to DSS-administered mice as described in Materials and Methods." (PMID 30539029, 2018). "In fact, IL-33 appears to enhance intestinal inflammation in the acute phase of DSS colitis and possibly in UC patients which are driven by Th2 type and innate immune responses." (PMID 30539029, 2018). "Consistent with the antitumor role of IL-33, IL33-deficient mice are highly susceptible to colitis and colitis associated cancer." (PMID 29499051, 2018). "In support of these data, genetic deletion of either ST2 or IL-33 precipitated more severe chemically induced colitis in these mice." (PMID 29922293, 2018). "Our findings, therefore, imply that IL-33 contributes to the resolution of colitis via modulation of macrophages and plays a crucial protective role in IBD." (PMID 28404987, 2017). "In conclusion, our studies here demonstrate that IL-33 treatment substantially ameliorates the development of TNBS-induced experimental colitis by priming macrophage to AAM." (PMID 28423665, 2017). "In conclusion, our data provide clear evidence that IL-33 plays a protective role in TNBS-induced colitis, which is closely related to AAM polarization." (PMID 28423665, 2017). "Here, we present novel evidence suggesting that IL-33 primes macrophage into alternatively activated macrophages (AAM) in TNBS-induced colitis." (PMID 28423665, 2017). "Previously, we have reported that IL-33 functions as a protective modulator in TNBS-induced colitis, which is closely related to a Th1-to-Th2/Treg switch." (PMID 28423665, 2017). "Our data suggest that IL-33 facilitates wound healing and ameliorates colitis via modulating the differentiation of goblet cells and M2 macrophages independent of the MyD88 pathway and T-cells." (PMID 28404987, 2017). "In the present study, we sought to dissect the role of IL-33 in de novo generation of AAM during the development of colitis." (PMID 28423665, 2017).
colitis (continued). "Overall, these observations suggest that IL-33 directly induces M2 macrophage polarisation and plays an important role in mucosal wound healing during colitis via the polarisation of M2 macrophages." (PMID 28404987, 2017). "Accompanied with increased AAM in peritoneal cavity, a specific abundance of F4/80+CD206+ double positive cells was observed in the lamina propria (LP) of colonic tissues from colitis mice with IL-33 treatment." (PMID 28423665, 2017). "IL-33 appears to have a protective effect in trinitrobenzene sulfonic acid-induced colitis, mostly driven by a Th1 immune response." (PMID 28710436, 2017). "Recently, it was reported that IL-33 colocalised with F4/80+ myeloid-derived cells in the inflamed intestinal lamina propria of mice in an oxazolone colitis model." (PMID 28404987, 2017). "IL-33 has also been reported to increase expression of the growth factor amphiregulin to enhance colonic mucin responses in DSS-induced colitis model." (PMID 28710436, 2017). "To assess the effects of IL-33 on enterocyte differentiation early in colitis and the contribution of MyD88 to these effects, we i.p. injected wild-type or MyD88-deficient mice with mrIL-33 after low-dose TNBS administration." (PMID 28404987, 2017). "In this study, we further confirmed the protective role of IL-33 in the development of TNBS-induced colitis." (PMID 28423665, 2017). "To this end, we assessed the effect of IL-33 on colitis using well-established acute murine models of colitis." (PMID 28404987, 2017). "We found that patients with IBD show decreased serum levels of IL-33 compared with healthy individuals and that IL-33 can attenuate colitis and aid tissue repair in mice." (PMID 28404987, 2017). "Previous findings have revealed a protective role for IL-33 in the development of TNBS-induced colitis via promoting a switch from intestinal Th1 to Th2/Treg responses." (PMID 28423665, 2017). "Here, we also observed that transfer of IL-33-induced AAM contributed to the sustaining the mucosal inflammation in TNBS-induced colitis." (PMID 28423665, 2017). "These mice were sacrificed before the development of severe colitis to investigate the effects of IL-33 at the onset of inflammation." (PMID 28404987, 2017). "In the mice model of IBD, ST2 gene KO mice showed a significantly improved signs of colitis, and IL-33 treatment impaired epithelial barrier permeability in vitro and in vivo." (PMID 28423665, 2017). "This is the first study to dissect the mechanisms by which IL-33 both directly and indirectly modulates the functions of enterocytes and macrophages in the context of mucosal healing and wound repair during colitis." (PMID 28404987, 2017). "In our recent study, an increased expression of IL-33 has been demonstrated in TNBS-induced mice colitis." (PMID 28423665, 2017). "In contrast, in the chronic DSS colitis model, weight recovery is markedly delayed in IL-33 knockout mice and the inflammation seems to be less severe when IL-33 is administered to the animals." (PMID 24701033, 2014). "While IL-33 injection in acute colitis led to certain aggravation of inflammation, it showed extenuating effects in chronic DSS-induced colitis due to a shift of Th1 to Th2 responses." (PMID 24491821, 2014). "The ultimate IL-33-induced expansion of Foxp3+ Tregs facilitates the observed decrease in the severity of colitis." (PMID 23062310, 2012). "Using the dextran sulfate sodium salt (DSS)-induced UC model and CCL5 knockout (Ccl5-KO) mice, we demonstrated that CCL5 deficiency exacerbates intestinal inflammation during the acute phase of colitis, partly due to impaired interleukin-33 (IL-33)-induced Treg formation." (PMID 41433131, 2026). "Moreover, IL-1α-deficient mice significantly suppressed tumor growth in the context of IL-33 deletion-induced colitis, highlighting IL-1α’s crucial role in promoting colitis and tumor development." (PMID 40767963, 2025).
colitis (continued). "We speculate that these differences may be due to the different immunological properties of the colitis mouse model, which also reflects the diversity and complexity of the actions of IL-33." (PMID 37686309, 2023). "Vice versa, however, IL-33 has been also reported to promote experimental colitis." (PMID 37635158, 2023). "Sedhom’s experiments using DSS and TNBS-induced colitis models in ST2−/− mice (C57BL/6J) demonstrated that IL-33 has a detrimental effect on intestinal epithelial cells, increasing their permeability and bacterial translocation and leading to more severe intestinal inflammation." (PMID 37686309, 2023). "We also found a modest but significant increase in IL-33 levels in our colitis model." (PMID 37289222, 2023). "During acute colitis in mice, IL-33 and Reg3γ are highly expressed in the colon." (PMID 37524871, 2023). "Moreover, IL-33 mediated regulatory T-cell differentiation and restricted the IL-23 signaling pathway in a bacteria-driven colitis model." (PMID 38058517, 2023). "IL-33 has been reported to exacerbate TNBS-induced colitis by promoting a Th1 response." (PMID 37691056, 2023). "Similarly, IL-33, a newly identified cytokine, has been shown to control the Th1 effector response and the action of the colonic Tregs in animal models of colitis and patients with IBD." (PMID 37443579, 2023). "Interestingly, IL-33 protects against haptenizing molecule 2,4,6-trinitrobenzene sulfonic acid-induced colitis in mice by enhancing autophagy through the TLR4-dependent signaling pathway." (PMID 36129262, 2022). "Accordingly, IL-33-deficient mice developed a dysregulated gut microbiota, and altered gut microbiota in IL-1α-knockout mice resulted in protection against DSS-induced colitis." (PMID 36339623, 2022). "Expression of IL-33 in the epithelial cells is suppressed by the signaling protein Sprouty2 via the PI3K-Akt pathway and accordingly, loss of Sprouty2 in the colon protects mice from DSS-induced colitis." (PMID 36189323, 2022). "However, there was also a contradictory report illustrating IL‐33 administration aggravated DSS colitis by amplifying Th2 response and increasing the number of IMφs." (PMID 35593111, 2022). "However, the results of another study showed that IL-33 had a protective effect against DSS-induced colitis by enhancing the expansion of ILC2 and Treg cells." (PMID 35410210, 2022). "Recombinant IL-33 administration during the chronic or recovery phase improved DSS-induced colitis." (PMID 36614065, 2022). "One study found that IL-33 deficiency impaired the differentiation of ILC2 and Th17 cells, and reduced levels of cytokines such as IL-6 and IL-1, which protected mice against DSS-induced colitis." (PMID 35410210, 2022). "Therefore, we investigated the role of IL-33 during intestinal inflammation and its potential as a novel therapeutic target in colitis." (PMID 34335571, 2021). "To better understand the lack of an effect of Il33 deficiency on colitis in Il10−/− mice, we examined colon Il33 expression in WT and Il10−/− mice at 12 and 30 weeks of age." (PMID 33953267, 2021). "Taken together, these data suggest that the protective effect of IL-33 during colitis could be, at least in part, dependent on Tregs." (PMID 34335571, 2021). "In addition, we found that curcumin promoted the release of the anti-inflammatory cytokines IL-10 and IL-33 in colitis mice and inhibited the secretion of the proinflammatory cytokines CCL-2, IL-1β, and IL-6." (PMID 34567209, 2021). "In our study, we could demonstrate, by using DEREG mice, that the specific depletion of Foxp3+ Tregs partially abrogated the positive effects of IL-33 administration in DSS colitis." (PMID 34335571, 2021). "This increase in citrine+ cells was due to a generalized increase in CD45−CD90+ fibroblasts in the colon, but not due to a higher percentage of fibroblasts expressing IL-33, indicating that both IL-33+ and IL-33− fibroblasts are increasing during DSS-induced colitis." (PMID 33953267, 2021).